C9orf72 (C9orf72-SMCR8 complex subunit)
Diseases named in the same sentence as C9orf72 in open-access papers (continued):
Sharing a sentence is not in itself a finding about the gene and the disease.
proteinopathies (28 papers, 2012 to 2025). "For instance, TARDBP mutations, TDP-43 proteinopathy and C9orf72 expansion are common to all three pathologies." (PMID 26300727, 2015). "Similar to TDP-43 proteinopathy, C9ORF72 pathology may act through loss-of-function (C9orf72 haploinsufficiency) and gain-of-function mechanisms." (PMID 34943897, 2021). "Identification of CSPG4 through proximity labeling extends this concept to C9orf72-associated ALS/FTD, suggesting convergence of pathogenic mechanisms across multiple proteinopathies." (PMID 41394638, 2025). "To evaluate the ability of TDP‐43_SAA to detect TDP‐43 proteinopathies, we compared 30 patients with GRN and C9orf72 mutations with the other 29 subjects of the cohort (including the 27 CTRLs and the 2 patients with MAPT mutations)." (PMID 41399249, 2025). "This is in accordance with the underlying proteinopathy, as GRN and C9ORF72 genetic patients are associated with a TDP-43 deposition, whereas MAPT genetic patients are characterized by a tau protein deposition." (PMID 36499048, 2022). "Specifically, C9orf72 neuropathology is classified as TDP-43 proteinopathy (Tar DNA binding protein of 43), since most ALS cases and half of FTD cases are characterized by inclusions consisting of the TDP-43 in glia and neurons." (PMID 34362180, 2021). "Familial forms of ALS that exhibit TDP-43 proteinopathy include the rare cases that are caused by mutations in the TDP-43 protein coding region, and those caused by C9orf72 repeat expansions, which is the most common genetic cause of ALS and FTD in the USA." (PMID 34723963, 2021). "Current studies in this field have focused on the pathogenesis driven by TDP-43 proteopathy, the complex pathogenesis of C9orf72 gene repeat amplification, RNA metabolism and impaired nucleoplasmic transport, defects in autophagy-lysosome pathway, and neuroinflammation and microglia/astrocyte roles." (PMID 40629595, 2025). "On the contrary, no family history was observed for parkinsonian syndromes confirming the hypothesis that, although C9orf72 HRE can be observed in ALS-plus phenotypes, the mutation is strictly related to TDP-43 proteinopathies." (PMID 36308529, 2023). "Patients with C9orf72 are known to have TDP-43 proteinopathy, but whether there is further crossover between C9orf72 pathology and other ALS subtypes has yet to be revealed." (PMID 35409306, 2022). "An increasing body of evidence indicates that TDP-43 proteinopathy underlies motor neuron degeneration caused by diverse genetic defects in various hereditary ALS, including ubiquilin 2, profilin-1, optineurin, valosin-containing protein (VCP), and C9ORF72." (PMID 23300771, 2012). "Furthermore, animal models of C9orf72 expansion toxicity also can exhibit TDP-43 proteinopathy." (PMID 34723963, 2021). "Among the TDP-43 proteinopathies, the peculiarity of C9ORF72 pathology is that the inclusion bodies also contain dipeptide repeat polymers (DPR) and both loss- and gain- of function (LOF and GOF) of the C9ORF72 protein have been suggested to cause neurodegeneration." (PMID 32487123, 2020). "FTLD‐TDP, manifested as sporadic (sFTLD‐TDP) or linked to mutations in various genes including expansions of the non‐coding region of C9ORF72 (c9FTLD), as well as sporadic ALS (sALS), are the most common TDP‐43 proteinopathies." (PMID 33332650, 2021). "Importantly, it is still not clear whether sporadic and familial cases, or even the different mutations with converging proteopathies (e.g., GRN or C9orf72), share the same pathophysiological processes, which can ultimately impact the body-fluid biochemical profiles." (PMID 34680117, 2021). "C9orf72-related neurodegeneration is a clinically and pathologically heterogeneous syndrome that is characterized by a combination of TDP-43 proteinopathy and superimposed extramotor p62-positive, TDP-43-negative pathology." (PMID 30550541, 2018).
proteinopathies (continued). "We will then discuss how phase separation may impact the major pathological feature of C9orf72-ALS/FTD, TDP-43 proteinopathy, and how LLPS may be targeted therapeutically in disease." (PMID 33967699, 2021). "C9orf72-mutation carriers exhibited none or limited 18F-Flortaucipir retention, indicating that 18F-Flortaucipir binding in TDP-43 proteinopathies is not a general TDP-43 related phenomenon." (PMID 30988363, 2019). "This variation could be explained by the inclusion of different FTD biochemical profiles, which likely differ between sporadic and familial cases with the same proteopathy, or even between genetic backgrounds of the same pathological subtypes (e.g., GRN and C9orf72)." (PMID 40866991, 2025). "In patients with mutations in the C9orf72-gene, only very limited 18F-Flortaucipir retention could be detected, indicating that binding of 18F-Flortaucipir in TDP-43 proteinopathies is not a general TDP-43 related phenomenon." (PMID 30988363, 2019). "Although TDP‐43 proteinopathies are the pathological hallmark of ALS regardless of patients' genotypes, with TDP‐43 deposition observed in astrocytes in post‐mortem tissues no post‐mortem studies have yet reported TDP‐43 proteinopathies in astrocytes in C9orf72‐related ALS." (PMID 31841614, 2020).
Atrophy (27 papers, 2014 to 2025). Any weakening or degeneration, especially through lack of use. "Neuroimaging studies have shown that individuals with the C9orf72 mutation exhibit symmetry patterns of atrophy in frontal, temporal, and parietal lobes, in contrast to asymmetric atrophy observed in GRN-mutated individuals." (PMID 41516057, 2025). "The C9orf72 repeat expansion has been reported to associate with atrophy of the more posterior and subcortical brain areas, including cerebellum, occipital and parietal cortex, thalamus, and the striatum, even at the presymptomatic phase." (PMID 35377014, 2022). "The early involvement of subcortical regions is a specific atrophy pattern in asymptomatic C9orf72 mutation carriers that distinguishes them from other FTLD mutation carriers." (PMID 32184751, 2020). "Even in regions where the rate of volume loss increased between the mild and symptomatic stages in C9orf72+ carriers, the magnitude of acceleration of atrophy between these 2 stages was much higher in MAPT+ and GRN+ carriers." (PMID 33112398, 2020). "We find the most severe atrophy in the anterior temporal lobes of subjects with svPPA, whereas C9orf72-mutation carriers instead show a more modest fronto-temporal atrophy." (PMID 30988363, 2019). "C9orf72 repeat expansion carriers had a greater degree of atrophy, as compared to GRN mutation carriers and MAPT mutation carriers, with the latter being the smallest group in our sample." (PMID 28460069, 2017). "On the other hand, C9orf72 mutation carriers tend to have a more generalized and symmetrical atrophy." (PMID 26388768, 2015). "Brain imaging showed a symmetrical pattern of atrophy, which would be in keeping with an expansion in C9orf72, whereas GRN mutations show a more asymmetrical pattern of atrophy." (PMID 24286341, 2014). "However, there was an additional association with thalamus atrophy in the C9orf72 mutation carriers, a region long associated with episodic memory function." (PMID 35950369, 2022). "The strongest association between C9orf72 expression and the atrophy pattern in symptomatic chromosome 9 open reading frame 72 repeat extension carriers was measured with microarray probe CUST_7641_PI416261804, which showed a non-significant negative association z = −0.27 (PFDR=0.23)." (PMID 33210084, 2020). "Overall cervical cord atrophy was detected in pre-symptomatic VAPB carriers, and cervical cord WM was atrophy identified in pre-symptomatic C9orf72 hexanucleotide repeat expansion carriers." (PMID 39596864, 2024). "C9orf72‐linked FTD‐ALS patients were found to present parietal and occipital lobe atrophy using structural MRI scans." (PMID 36971206, 2023). "In C9orf72 mutation carriers, FER test score was positively associated with bilateral insula involvement, as well as atrophy in the left frontal lobe (middle frontal gyrus and orbitofrontal cortex), left basal ganglia (putamen and caudate) and right amygdala." (PMID 33221702, 2020). "Further, the C9orf72-cases have a shorter disease duration and a lower degree of atrophy compared to the svPPA cases." (PMID 30988363, 2019). "Finally, not all scanners were able to accommodate measuring perfusion within the cerebellum, a region that has been noted to feature some atrophy in C9orf72 carriers." (PMID 38623902, 2024). "Whether TE activation can be measured in peripheral blood and how the reduction in peripheral C9orf72 expression observed in HRE carriers relates to atrophy and clinical impairment remain unknown." (PMID 36446586, 2023). "Moreover, we identified disproportionate atrophy of the right mediodorsal lateral nucleus in HRE carriers and showed that C9orf72 expression associated with clinical severity, independent of thalamic atrophy." (PMID 36446586, 2023). "It is unclear why fewer are seen in these two groups although this may be related to underlying atrophy of the basal ganglia which tends to be seen in the GRN and MAPT groups to a greater extent than in the C9orf72 group." (PMID 28529873, 2017).
Atrophy (continued). "A study of Australian FTLD cases finds lessened atrophy and slower disease progression in C9orf72." (PMID 28877758, 2017). "A relatively mild and slowly progressing atrophy, characterized by a predominantly frontal rather than temporal epicenter of GM alterations, has previously been reported also in bvFTD associated with a C9orf72 mutation and in presymptomatic C9orf72 carriers." (PMID 41319328, 2025). "Other recommendations include using validated visual atrophy rating scales and volumetric analyses of brain regions on MRI, 18F-fluorodeoxyglucose PET, neurofilament light chain in serum or cerebrospinal fluid (CSF), and screening for C9orf72 mutation in patients with prevalent psychiatric symptoms." (PMID 34552551, 2021). "Compared with controls, both sporadic bvFTD and bvFTD C9orf72 carriers showed significant atrophy in all thalamic regions (except for VPL and VM), with the C9orf72 group showing more extreme values." (PMID 35326292, 2022). "Using an average of the best performing direct measure, the current study reports a similar pattern of results, with annual atrophy rates of 1.8 (0.9)% in MAPT, 1.6 (1.1)% for C9orf72 and 3.1 (2.0)% for GRN patients, who conclusively exhibit the highest rate of change across subgroups." (PMID 34626889, 2021). "The individual with bvFTD due to GRN mutation showed largely similar results on the SUVR map as sporadic and C9orf72 bvFTD but had loci of elevated binding in the superior cerebellum and the temporal lobe that overlapped but did not correspond to observed atrophy." (PMID 36513817, 2023). "These maps and plots revealed that variability was highest in MAPT+ and lowest in C9orf72+ carriers, suggesting that excessive variability across C9orf72+ carriers, either in the spatial location of atrophy or the rate of atrophy, does not account for the group-level findings." (PMID 33112398, 2020). "The MD increases were more widespread than the detected atrophy in the symptomatic GRN and MAPT groups, but not for C9orf72 expansion carriers." (PMID 41245435, 2025).
familial amyotrophic lateral sclerosis (27 papers, 2014 to 2026). An instance of amyotrophic lateral sclerosis that is caused by an inherited modification of the individual's genome. "An expansion of the GGGGCC hexanucleotide in the non-coding region of C9orf72 represents the most common cause of familial amyotrophic lateral sclerosis." (PMID 37006326, 2023). "Given that C9orf72 mutation is the most common risk factor for familial amyotrophic lateral sclerosis and FTLD, its strong association with TDP‐43 pathology has been established." (PMID 34823271, 2022). "Here we provide evidence demonstrating pathogenic differences in CSF from patients with sporadic amyotrophic lateral sclerosis and familial amyotrophic lateral sclerosis patients with mutations in SOD1, C9orf72 and TARDBP." (PMID 36043141, 2022).
spinocerebellar ataxia (21 papers, 2012 to 2025). "Two siblings of Guyanese ancestry who developed ataxia, parkinsonian symptoms and dementia were identified carrying both an expanded allele of C9orf72 and ATXN2 (37/22 repeats)." (PMID 38254109, 2024). "However, the spectrum of neurological conditions associated with the repeat expansion in C9orf72 is very broad, including rarely cerebellar ataxias." (PMID 29316893, 2018). "There could be a direct effect of expression levels of isoforms of C9orf72, or a “trans”-like effect through RNA-toxicity, as shown in other repeat expansions diseases including fragile X-associated tremor/ataxia syndrome (FXTAS)." (PMID 22509407, 2012). "For instance, the repeat expansion in the C9orf72 gene is present in fewer than 10% of ALS patients and many ataxias can be caused by expansions of a variety of repeats." (PMID 32345345, 2020). "By analogy to other repeat expansion disorders, such as Fragile X Syndrome and Freidriech’s Ataxia, we hypothesized that DNA-RNA hybrids or R-loops formed by an expanded C9ORF72 transcript lead to epigenetic silencing." (PMID 28606110, 2017). "Extensive genetic testing has been performed in various cases, which included ALS genes (C9orf72, FUS, SOD1, TARDBP), oculopharyngeal muscular dystrophy (PABPN1), Kennedy disease (AR), panels for spinocerebellar ataxia as well as whole-exome sequencing." (PMID 33842068, 2021). "These unrelated ataxia patients were subsequently assayed for repeat expansions in SCA8, SCA10, SCA12, SCA36, FXTAS and C9orf72." (PMID 29316893, 2018). "Post-mortem studies that confirmed cerebellar involvement in C9orf72 highlighted the absence of overt ante mortem cerebellar signs such as ataxia without considering cognitive manifestations." (PMID 33983551, 2021). "However, similar repeat expansion has been proven to be the cause of many other neurodegenerative diseases such as fragile X syndrome (FXS), several types of spinocerebellar ataxia (SCA31 and SCA37), C9orf72-related disorder, and, most recently, neuronal intranuclear inclusion disease (NIID)." (PMID 32174879, 2020). "The results do not support genetic testing for C9orf72 expansion in ataxia patients." (PMID 29316893, 2018). "Interruptions in C9orf72 expansions have not yet been described, but interrupted repeat expansions have frequently been detected in other neurological disorders, including spinocerebellar ataxia, fragile X syndrome, myotonic dystrophy type I and Friedreich ataxia." (PMID 28550099, 2017). "Finally, our study does not support genetic testing for C9orf72 expansion in ataxia patients." (PMID 29316893, 2018).
autoimmune disease (17 papers, 2018 to 2025). A disorder resulting from loss of function or tissue destruction of an organ or multiple organs, arising from humoral or cellular immune responses of the individual to their own tissue constituents. "Despite the established relation between loss of function of C9orf72 and autoimmunity, only one prior study has reported an increased incidence of autoimmune diseases in carriers of the C9ORF72 HRE." (PMID 40149460, 2025). "For example, the type I interferon (IFN) cluster of 17 genes, including IFNk adjacent to C9orf72, are linked to autoimmune diseases (e.g. dysregulated inflammation, lupus, rheumatoid arthritis, diabetes and multiple sclerosis)." (PMID 39669124, 2024). "Loss-of-function of C9orf72 lead to fatal autoimmune diseases in mice, indicating the role of C9orf72 in immune regulation." (PMID 38504981, 2024). "Mice depleted for one or both copies of C9orf72 were more susceptible to EAE, which reflects susceptibility to autoimmune diseases in C9orf72 caused by ALS and FTD." (PMID 35979366, 2022). "Intermediate C9ORF72 expansions have been associated with autoimmune diseases and susceptibility to severe infectious diseases, in accordance with the role of this gene in immune responses." (PMID 35353274, 2022). "Different experimental mouse models have shown that loss-of-function of 3110043O21Rik gene, the mouse ortholog of C9ORF72 (referred from here as C9orf72), causes a severe immune dysregulation including lymphadenopathy, splenomegaly, and autoimmune disease." (PMID 33287823, 2020). "Furthermore, mice harboring loss-of-function mutations in the ortholog of C9orf72 cause fatal autoimmune diseases." (PMID 33541344, 2021). "C9orf72 is the most common genetic background of FTD, and its causal relationship with autoimmune diseases remains uncertain." (PMID 38125810, 2023). "The C9orf72 knockout mouse models do not exhibit neurodegeneration, but display immune system dysfunction and develop autoimmune disease-like phenotypes, suggesting that C9orf72 is a central regulator in the immune system." (PMID 34799692, 2022). "While this observation might simply reflect the generally higher incidence of autoimmune diseases in females, emerging evidence highlights a critical role of C9ORF72 in immunity." (PMID 40149460, 2025). "Immunological disease could potentially develop by alterations in the expression of C9orf72, it has been shown that mice with C9orf72 knockdown develop a fatal autoimmune disease." (PMID 36936421, 2023). "Additionally, C9orf72 depletion results in autoimmune disease via the autophagy-lysosome pathway 34-36." (PMID 36438488, 2022). "A similar increased risk of autoimmune disorders was also observed in a cohort of FTD patients with TDP-43 pathology, and subsequently in a cohort of specifically C9orf72 gene mutation carriers, compared to normal controls or subjects with other neurodegenerative diseases." (PMID 30465257, 2019). "In addition to C9orf72, GRN mutations have also been linked to autoimmunity with multiple studies reporting prominent upregulation of serum progranulin levels in patients with various autoimmune diseases." (PMID 34360544, 2021). "Our finding that C9orf72 and Smcr8 mutually stabilize one another provided a key opportunity to resolve whether removing the function of this complex was indeed sufficient to lead to inflammatory and autoimmune disease." (PMID 29950492, 2018). "Studies utilizing C9orf72−/− have found broad phenotypic overlap, characteristic of an autoimmune disease but not neurodegeneration." (PMID 39318236, 2025). "Moreover, in our study, we observed a significantly higher incidence of autoimmune diseases in the C9ALS cohort, a result in line with the biological data on autoimmune phenotype in C9ORF72 knockout mouse models." (PMID 40149460, 2025).
autoimmune disease (continued). "Some studies have shown that in the Finnish population, carriers of FTD C9orf72 expansion are less likely to develop autoimmune diseases than noncarriers, which provides some suggestive evidence for the associations between autoimmune disease and FTD." (PMID 38125810, 2023). "Further connecting C9orf72 expansion carriers to autoimmune disease, in a small cohort of patients diagnosed with the rare combination of multiple sclerosis and ALS, a remarkable 80% carried the hexanucleotide repeat expansion in C9orf72." (PMID 30465257, 2019).